ZNF674-AS1 (ZNF674 antisense RNA 1)
Gene: Long non-coding RNA gene on chromosome X (46,545,438 to 46,564,575, forward strand). Ensembl gene ENSG00000230844.
Diseases named in the same sentence as ZNF674-AS1 in open-access papers:
ZNF674-AS1 is named in the same sentence as 1 disease in open-access papers, as found by Europe PMC text mining. Sharing a sentence is not in itself a finding about the gene and the disease. The quoted sentences say what the papers report.
hepatocellular carcinoma (1 paper, 2021). A malignant tumor that arises from hepatocytes. "The lncRNA ZNF674 antisense RNA 1 (ZNF674-AS1) is downregulated in hepatocellular carcinoma (HCC)." (PMID 33618674, 2021).